JOSD1 (Josephin domain containing 1)
Diseases named in the same sentence as JOSD1 in open-access papers:
JOSD1 is named in the same sentence as 32 diseases in open-access papers, as found by Europe PMC text mining. Sharing a sentence is not in itself a finding about the gene and the disease. The quoted sentences say what the papers report.
cervical cancer (3 papers, 2018 to 2025). A primary or metastatic malignant neoplasm involving the cervix. "Previously, the DUBs OTUD1 and JOSD1 had been shown to regulate Mcl-1 expression in cervical cancer cells." (PMID 33627786, 2021). "Two other deubiquitinating enzyme, OTUD1 and JOSD1, have also been shown to regulate Mcl-1 in cervical cancer, suggesting that the regulation of Mcl-1 ubiquitination may be essential for cervical cancer progression." (PMID 40011575, 2025). "Although the effects of COPS5 knock-down in SNAIL expression was most predominant amongst the candidates in lung adenocarcinomas, the other four DUBs (JOSD1, OTUB1, OTUD7A, and OTUD7B) could potentially regulate SNAIL expression in other cancer such as cervical cancers." (PMID 29755680, 2018).
gynecological cancer (3 papers, 2021 to 2024). "The association of JOSD1 with the development of chemoresistance in gynecological cancer makes it the subject of a potential biomarker and therapeutic target." (PMID 33479176, 2021). "Upregulated JOSD1 contributes to the acquisition of chemo-resistance by inhibiting mitochondrial apoptotic signaling in gynecological cancer by stabilizing MCL1." (PMID 39766302, 2024). "Depletion of JOSD1 leads to the death of gynecological cancer cells." (PMID 39766302, 2024). "Importantly, it has recently been shown that elevated JOSD1 levels are found in gynecological cancers and this correlates with poor prognosis." (PMID 33479176, 2021).
melanoma (3 papers, 2021 to 2024). A malignant, usually aggressive tumor composed of atypical, neoplastic melanocytes. "Mutations in JOSD1 gene have been identified in melanoma, endometrial, bladder, and ovarian cancers." (PMID 38012642, 2023). "The genetic aberrations of JOSD1 have presented in multiple cancers, particularly in melanoma, uterine, bladder, and ovarian cancer." (PMID 34261480, 2021). "For example, the gene amplification of JOSD1 was observed in uterine cancer and melanoma." (PMID 39143074, 2024).
acute myeloid leukemia (2 papers, 2022 to 2023). Acute myeloid leukemia (AML) is a group of neoplasms arising from precursor cells committed to the myeloid cell-line differentiation. "A small molecule inhibitor of JOSD1 was shown to induce cell death of JAK2-V617F-positive primary acute myeloid leukemia (AML) cells." (PMID 37892185, 2023). "In acute myeloid leukemia (AML) cells, JOSD1 interacts with JAK2-V617F and promotes its expression." (PMID 36159990, 2022). "JOSD1 was found to be up-regulated in the head and neck squamous cell carcinoma (HNSCC), gynaecological cancer (GC) cells, and acute myeloid leukemia (AML) cells." (PMID 36159990, 2022).
colon cancer (2 papers, 2023 to 2024). "Our study concludes that JOSD1 is associated with a genetic signature of Hippo signaling and correlates with poor survival in colon cancer." (PMID 39143074, 2024). "Consistently, the reduction of YAP levels in colon cancer cells correlated with a notable decrease in both JOSD1 mRNA and protein levels." (PMID 39143074, 2024). "Given the widespread use of 5-FU in the treatment of colon cancer, we knocked down JOSD1 and observed that HCT116 cells exhibited decreased drug resistance." (PMID 39143074, 2024). "Our study uncovers novel regulatory mechanisms by which JOSD1 regulates the Hippo pathway in colon cancer." (PMID 39143074, 2024). "The CCK8 assay demonstrated significant inhibition of colon cancer cell growth with JOSD1 deletion, while the EdU doping assay revealed a marked decrease in colon cancer cell proliferation due to JOSD1 deletion." (PMID 39143074, 2024). "We inhibited YAP degradation using the proteasome inhibitor MG132 and found that removal of JOSD1 decreased YAP protein levels in colon cancer cells." (PMID 39143074, 2024). "We carried out IHC (Immuno-histochemistry) to investigate the expression of JOSD1 with clinical characteristics in colon cancer sample, in which JOSD1 expression correlated with tumor invasion, lymph node invasion and distant metastasis." (PMID 39143074, 2024). "It was observed that JOSD1 facilitates the progression of colon cancer by modulating the deubiquitination of the YAP K48 linkage, thereby amplifying Hippo/YAP activity." (PMID 39143074, 2024). "This sequence of events collectively highlights the potential regulatory role of YAP in modulating JOSD1 expression in colon cancer cells." (PMID 39143074, 2024). "The transwell experiments demonstrated that the invasive ability of colon cancer cells was significantly reduced upon removal of JOSD1." (PMID 39143074, 2024). "Further survival analysis from KMPLOT database showed JOSD1 expression correlated with poor survival in colon cancer patients." (PMID 39143074, 2024). "Through correlation analysis of DUBs (deubiquitinases) expression and Hippo target gene signature in colon cancer samples, we found JOSD1 as a critical deubiquitinase for Hippo signaling and colon cancer progression." (PMID 39143074, 2024). "From the TCGA colon cancer samples, JOSD1 expression positively correlated with YAP target gene signature (NES = 1.75; P < 0.05)." (PMID 39143074, 2024). "In addition, long-term clonogenesis experiments demonstrated that JOSD1 depletion inhibits colon cancer growth, and this inhibitory effect can be reversed by YAP overexpression." (PMID 39143074, 2024). "Likewise, findings from wound healing experiments suggested that the migration ability of colon cancer cells was significantly impeded upon JOSD1 deprivation." (PMID 39143074, 2024). "In addition, in the FACS analysis, JOSD1 depletion was found to elevate cell apoptosis in colon cancer cells." (PMID 39143074, 2024). "Moreover, results from the transwell experiment indicated that the invasive capacity of colon cancer cells was compromised upon JOSD1 exhaustion." (PMID 39143074, 2024). "Consequently, a positive regulatory loop between JOSD1 and Hippo signaling has been identified, underscoring their interdependence during colon cancer progression." (PMID 39143074, 2024). "The results showed that silencing JOSD1 inhibited the tumorigenic potential of colon cancer cells." (PMID 39143074, 2024). "JOSD1 could facilitate colon cancer progression and in colon cancer, inhibition of JOSD1 via shRNA has been demonstrated to impede tumorigenesis." (PMID 39143074, 2024). "Deletion of JOSD1 in colon cancer cells resulted in a decrease in the half-life of YAP protein." (PMID 39143074, 2024). "Furthermore, subsequent experiments involving the depletion of YAP in colon cancer cells demonstrated a significant reduction in YAP binding to the JOSD1 promoter region, as evidenced by the ChIP assay results." (PMID 39143074, 2024).
colon cancer (continued). "Furthermore, wound healing assays indicated that silencing JOSD1 impeded the migration of colon cancer cells." (PMID 39143074, 2024). "Blocking JOSD1 and impeding the positive cycle may be a promising strategy for colon cancer treatment." (PMID 39143074, 2024). "Considering the significance of JOSD1 in colon cancer, blocking JOSD1 may be a viable strategy for treating colon cancer." (PMID 39143074, 2024). "The xenograft mouse model further demonstrated that the inhibition of JOSD1 could effectively suppress colon tumor growth in vivo." (PMID 39143074, 2024). "Thus, the JOSD1 could facilitate YAP function in colon cancer cells, which depended on its ubiquitin peptidase activity." (PMID 39143074, 2024). "In addition, endogenous immunoprecipitation experiments demonstrated that JOSD1 could interact with YAP in colon cancer cells." (PMID 39143074, 2024). "We selected two colon cancer cell lines, HCT116 and SW480, and investigated the phenotype of JOSD1 in these cell lines." (PMID 39143074, 2024). "Thus, targeting JOSD1 may represent a promising therapeutic approach for managing colon cancer." (PMID 39143074, 2024). "The study examined the localization of JOSD1 and YAP in colon cancer cells." (PMID 39143074, 2024).
colorectal cancer (2 papers, 2023 to 2024). A primary or metastatic malignant neoplasm that affects the colon or rectum. "In summary, this study identified forward feedback between the Hippo pathway and JOSD1 that drives colorectal cancer progression." (PMID 39143074, 2024). "Therefore, we conclude that JOSD1 plays a crucial role in the progression of colorectal cancer cells." (PMID 39143074, 2024). "Therefore, JOSD1 controls the advancement of colorectal cancer cells via the Hippo/YAP pathway." (PMID 39143074, 2024). "One probe mapped to JOSD1 (cg03088955), a disubiquination enzyme with a role in autophagy, and another mapped to PIP4KA2 (cg09273683), a gene with an SNP that was found to be an environmental interactor between smoking and colorectal cancer." (PMID 37331566, 2023).
head and neck squamous cell carcinoma (2 papers, 2021 to 2022). A squamous cell carcinoma that arises from any of the following anatomic sites: lip and oral cavity, nasal cavity, paranasal sinuses, pharynx, larynx, and salivary glands. "Previous studies have demonstrated that DUB Josephin Domain Containing 1 (JOSD1) is implicated in tumor progression, however, the role and mechanism of JOSD1 in head and neck squamous cell carcinoma (HNSCC) remain to be explored." (PMID 34261480, 2021).
leukemia (2 papers, 2024). A malignant (clonal) hematologic disorder, involving hematopoietic stem cells and characterized by the presence of primitive or atypical myeloid or lymphoid cells in the bone marrow and the blood. "Targeting JOSD1 using small molecule inhibition could be a novel targeted therapy for leukemias with mutant JAK2." (PMID 39766302, 2024). "Further research proposed that a small molecule target JOSD1 could a promising strategy in JAK2-mutant leukemia patients." (PMID 39143074, 2024). "JOSD1 was reported to stabilize MCL1 and inhibit mitochondrial-dependent apoptosis, which subsequently promoted chemotherapy resistance in leukemia." (PMID 39143074, 2024).
lung carcinoma (2 papers, 2023 to 2024). "In solid tumors, JOSD1 was found to stabilize Snail and promote lung cancer progression." (PMID 39143074, 2024). "While data on JOSD1 in NBT are lacking, JOSD1 can deubiquitinate and stabilize Snail protein to promote EMT and tissue invasion of lung cancer cells." (PMID 37892185, 2023).
osteoarthritis (2 papers, 2021 to 2023). A noninflammatory degenerative joint disease occurring chiefly in older persons, characterized by degeneration of the articular cartilage, hypertrophy of bone at the margins and changes in the synovial membrane. "Unk−/− mice were also prioritized as one of four lines with the strongest combined evidence for a key functional role in osteoarthritis pathogenesis, whereas Josd1−/− mice were one of seven lines with the most severely abnormal joint phenotype." (PMID 33473114, 2021). "It stabilizes SOCS1, an important negative regulator of cytokine signaling, and JOSD1 mRNA is upregulated in high-grade osteoarthritis cartilage, suggesting a protective role for JOSD1 in osteoarthritis." (PMID 33473114, 2021).
cholelithiasis (1 paper, 2025). The presence of crystallized deposits forming in the gallbladder or biliary tree, primarily composed of cholesterol, bilirubin, and bile. "Our findings imply that JOSD1 may play a significant role in the associative mechanisms between cholelithiasis and GERD via the deubiquitination processes." (PMID 40139907, 2025). "In general, we identified 3 putatively functional genes shared between cholelithiasis and GERD, including SUN2, CBY1, and JOSD1, overexpression of which was negatively associated with the risk of cholelithiasis and GERD in the esophagus-related tissues." (PMID 40139907, 2025). "The TWAS analysis showed that overexpression of SUN2, JOSD1, and CBY1 was negatively associated with the risk of cholelithiasis and GERD in the blood and esophagus-related tissues, while overexpression of JOSD1 and CBY1 was positively associated with these 2 diseases in the liver tissue." (PMID 40139907, 2025).
Fanconi anemia (1 paper, 2022). Fanconi anemia (FA) is a hereditary DNA repair disorder characterized by progressive pancytopenia with bone marrow failure, variable congenital malformations and predisposition to develop hematological or solid tumors. "For JOSD1, allograft rejection, Th17 cell differentiation, and tryptophan metabolism were significantly up-regulated, whereas DNA replication and fanconi anemia pathway were significantly down-regulated." (PMID 36159990, 2022).
hepatocellular adenoma (1 paper, 2022). A benign epithelial neoplasm arising from the hepatocytes. "The sub-types of with the highest proprotion of all alterations were Hepatocellular carcinoma plus Intrahepatic Cholangiocarcinoma, Hepatocellular Adenoma, and Hepatocellular carcinoma for ATXN3, ATXN3L, JOSD1, and JOSD2, respectively." (PMID 36159990, 2022).
hepatocellular carcinoma (1 paper, 2022). A malignant tumor that arises from hepatocytes. "Furthermore, we analyzed the co-expression of ATXN3, JOSD1 and JOSD2 in hepatocellular carcinoma using the GSCALite database, and analyzed the signaling pathways involved by MJDs family member respectively." (PMID 36159990, 2022).
liver diseases (1 paper, 2024). "Our study thus unveils JOSD1 as a potential candidate for ameliorating hepatocellular damage in liver diseases." (PMID 39284830, 2024). "However, the role of JOSD1 in liver diseases, particularly in proteotoxicity, is unknown." (PMID 39284830, 2024).
Machado-Joseph disease (1 paper, 2023). "Interestingly, most DUBs demonstrated dual selectivity, with one relevant exception, represented by JOSD1, a member of the Machado-Joseph disease (MJD) class." (PMID 37234921, 2023).
rectal cancer (1 paper, 2023). A primary or metastatic malignant neoplasm that affects the rectum. "In summary, we identified five radiosensitivity-related genes associated with rectal cancer prognosis: TOP2A, MATR3, APOL6, JOSD1, HOXC6." (PMID 38012642, 2023). "Through the random survival forest analysis of these 1153 differential genes, we finally screened five key genes, which were the radiosensitivity up-regulated genes of rectal cancer: TOP2A, MATR3, APOL6, JOSD1 and the radiosensitivity down regulated gene of rectal cancer: HOXC6." (PMID 38012642, 2023). "In subsequent studies, we will perform cell function experiments, xenograft experiments in nude mice, and molecular mechanism experiments on irradiated human rectal cancer cell lines after overexpression or knockdown of TOP2A, MATR3, APOL6, JOSD1, and HOXC6." (PMID 38012642, 2023). "qRT-PCR revealed that MATR3 expression was different in rectal cancer tissues and adjacent non-cancerous tissues, while APOL6, HOXC6, JOSD1, and TOP2A expression was not different." (PMID 38012642, 2023).
testicular tumors (1 paper, 2022). "Our results showed that ATXN3, JOSD1, and JOSD2 were markedly up-regulated in HCC samples, while ATXN3L was expressed only in testicular and testicular tumors." (PMID 36159990, 2022).
cancer (8 papers, 2011 to 2025). A tumor composed of atypical neoplastic, often pleomorphic cells that invade other tissues. "JOSD1 is implicated with membrane dynamics, cancer chemoresistance, and antiviral response, yet its physiological substrates are poorly defined." (PMID 33479176, 2021). "Josephin domain containing 1 (JOSD1) is a deubiquitinase that has been shown to prevent proteins from being marked for degradation in various cancers." (PMID 41353157, 2025). "Nevertheless, there is emerging evidence indicating that Ataxin-3, Ataxin-3L, JOSD1, and JOSD2 are also implicated in cancer progression." (PMID 32982735, 2020). "In contrast, mutational alteration of JOSD1 and JOSD2 in cancer is less common." (PMID 32982735, 2020). "USP43, USP52, JOSD1, UCHL5 and OTUB1 all reduced levels of the HIF-1α target CA9 in the secondary validation screen in two different non-cancer cell lines." (PMID 39009674, 2024). "E3 ubiquitin ligases (Mule, SCFβ-TrCP, SCFFBW7, TRIM17, APC/CCdc20, and FBXO4) and deubiquitinases (USP9X, Ku70, USP13, JOSD1, and DUB3) work together to balance MCL1 stability, which has an important role in the chemoresistance of cancer cells." (PMID 33803505, 2021).
tumor (7 papers, 2020 to 2024). "The function of JOSD1 was further assessed through an in vivo experiment using a xenograft tumor model." (PMID 39143074, 2024). "These gain-of-function amplifications of JOSD1 and JOSD2 are thought to cause elevated expression to promote their tumor-promoting functions." (PMID 32982735, 2020). "Additionally, JOSD1 suppression inhibited the tumor growth and improved chemosensitivity in vivo." (PMID 34261480, 2021). "Furthermore, we found the high expression of Ki67 in JOSD1-depleted xenografts, indicating that JOSD1 could accelerate tumor proliferation in HNSCC." (PMID 34261480, 2021). "The expression of JOSD1 was aberrant in HNSCC specimens, and its depletion improved cisplastin-induced apoptosis of HNSCC cells, suppressed tumour growth and improved chemosensitivity in vitro via regulation by the epigenetic regulator, BRD4." (PMID 39284830, 2024). "JOSD1 was overexpressed in lung adenocarcinoma (LUAD) tissues, and its knockdown suppressed tumour cell proliferation and inhibited metastasis." (PMID 39284830, 2024). "Patients receiving intensive chemotherapy of their NBT showed significantly reduced tumor tissue expression of USP24, USP34, MINDY2, USP8, JOSD1, USP52, and USP12 when compared to the observation group." (PMID 37892185, 2023). "Deubiquitinases USP9X, Ku70, JOSD1, DUB3/USP17L2, and USP13 have been described to stabilize Mcl-1, promote tumor cell survival and suppress apoptosis." (PMID 35301297, 2022). "In the TRAF4-knockout xenograft tumors, the introduction of JOSD1 markedly attenuated the antitumor effects of blocking TRAF4 even in the presence of IR, as demonstrated by the tumor growth rate, tumor mass and tumor weight, which significantly increased." (PMID 36535926, 2022). "Nevertheless, both JOSD1 and JOSD2 expression have been found to be significantly alterated in several tumor types." (PMID 32982735, 2020). "In our study, JOSD1 knockdown could inhibit the growth and colony formation of TSCCA and SCC25 cells, and suppress the tumor growth in vivo." (PMID 34261480, 2021). "The results showed that the xenografts generated from JOSD1-silenced TSCCA cells weighed significantly less than that generated from negative control cells, revealing an oncogenic role of JOSD1 in tumor growth of HNSCC." (PMID 34261480, 2021). "• JOSD1 and JOSD2 are amplificated in several tumor types and maybe potential therapy targets." (PMID 32982735, 2020).
gynecologic tumors (1 paper, 2023). "JOSD1 promotes chemoresistance by stabilizing MCL1 in gynecologic tumors." (PMID 38012642, 2023).
infection (1 paper, 2025). The state of being infected such as from the introduction of a foreign agent such as serum, vaccine, antigenic substance or organism. "LV Josd1-ps induced significant overexpression of lncJosd1-ps RNA in mouse podocytes assayed 72 h post infection, whereas ASO Josd1-ps induced significant downregulation of lncJosd1-ps RNA." (PMID 40072092, 2025).
JOSD1 also shares sentences with these, for which no sentence is quoted: ovarian carcinoma (2 papers); cholangiocarcinoma (1); esophageal cancer (1); gastric cancer (1); gastrointestinal tumors (1); intrahepatic cholangiocarcinoma (1); lung adenocarcinoma (1); prostate carcinoma (1); rectal adenocarcinoma (1); uterine cancer (1).